NLRP3 (NLR family pyrin domain containing 3)
Diseases named in the same sentence as NLRP3 in open-access papers (continued):
Sharing a sentence is not in itself a finding about the gene and the disease.
Hyperglycemia (continued). "MiR-223-2p was over-expressed in the hyperglycemia-induced cardiomyocyte injury cellular model; in addition, inhibiting miR-223-3p expression led to further activation of myocardial fibrosis and specific apoptotic pathways, including the attenuation of NLRP3 inflammasome in diabetic cardiomyopathy." (PMID 36869348, 2023). "In addition, hyperglycemia is able to trigger the NLRP3 inflammmasome." (PMID 37197172, 2023). "In addition, hyperglycemia may contribute to the activation of the NLRP3 inflammasome mediated by pyruvate kinase M2 (PKM2) in macrophages." (PMID 35719709, 2022). "A recent study described the role of disordered GM-atrial NLRP3 inflammasome axis in the pathogenesis of age-related AF, that the aging accompanied by elevated LPS and hyperglycemia was speculated as the potential factor which promotes the aged microbiota-induced AF." (PMID 35844801, 2022). "In addition, EMD treatment was confirmed to rescue normal shape and function of INS-1 cells during hyperglycemia via the inhibition of NLRP3/GSDMD signaling, suggesting EMD could regulate the upstream of GSDMD cleavage and suppress pyroptosis." (PMID 35265148, 2022). "Moreover, tPA may stimulate NLRP3 inflammasome activation by generating increased ROS after hyperglycemia-exacerbated I/R damage." (PMID 33735403, 2021). "In addition, except hyperglycemia, high lipid, insulin resistance, and hyperinsulinemia all contribute to pyroptosis in DbCM via increasing ROS, which is seen as a significant activator inducing the NLRP3 inflammasome." (PMID 35145423, 2021). "Thus, hyperglycemia induced NLRP3 inflammasome activation in liver KCs post‐TAA treatment." (PMID 31625631, 2020). "Therefore, suppression of NLRP3 inflammasome could be a potential target of hyperglycemia-induced renal damage." (PMID 32050658, 2020). "In the present study, high levels of IL-1β and NLRP3 inflammasome activation were observed in the hippocampus of the db/db mice and HG-induced hippocampal neurons, suggesting that hyperglycemia could activate NLRP3 inflammasome and induce hippocampal inflammation." (PMID 29507694, 2018). "Notably, we reported for the first time that IL-22 gene therapy not only suppressed the systemic pathogenesis of DN, including hyperglycemia and metabolic disorders, but also protected against renal pathogenesis via suppression of NLRP3 inflammasome activation." (PMID 28726774, 2017). "Similarly, NLRP3 inflammasome activation in pancreatic β-cells is triggered by hyperglycemia, and subsequent IL-1β production contributes to β-cell death, suggesting the NLRP3 inflammasome as a sensor of chronically elevated glucose and a mediator of pancreatic dysfunction." (PMID 23924318, 2013). "Levels of mitochondrial reactive oxygen species (mtROS), mitochondrial DNA (mtDNA), the NLRP3 inflammasome and pyroptosis were monitored in the hearts of DCM mice or H9c2 cardiomyoblasts induced by hyperglycaemia following ICA treatment." (PMID 42292806, 2026). "Studies have reported that hyperglycemia promotes the binding of Txnip and thioredoxin, leading to excessive oxidative stress and ROS production, then initiates DKD pyroptosis in a NLRP3 inflammasome-dependent manner." (PMID 40568564, 2025). "Hyperglycemia and elevated free fatty acids (FFA) can reciprocally activate the NLRP3 inflammasome, establishing a “metabolism-inflammation” positive feedback loop." (PMID 41245414, 2025). "NLRP3 inflammatory vesicles are involved in the pathogenesis of DKD and promote the development of DKD under advancing hyperglycemia conditions." (PMID 39000237, 2024). "Hyperglycaemia promotes high ROS production, which binds TXNIP to NLRP3, thereby promoting the activation of NLRP3 inflammasome." (PMID 38250736, 2023). "The results of this study indicate that β-asarone attenuates HG-stimulated NLRP3 inflammasome-mediated lytic cell death and inactivates NF-κB in ARPE-19 cells, indicating its potential to treat hyperglycemia-induced DR." (PMID 37507949, 2023).
Hyperglycemia (continued). "The specific pathology of the NLRP3 inflammasome in the heart suggests that it has emerged as a strong candidate to bridge inflammation and DCM, which is activated by ROS, hyperglycemia, hyperlipidemia, and advanced glycation end products during DCM." (PMID 36111168, 2022). "Similarly, the overexpression of ALDH2 could suppress the mitochondrial ROS production and inhibit the occurrence of NLRP3 inflammasome expression to protect the H9c2 cardiac cells against hyperglycemia-induced OS and inflammation, thus protecting cardiomyocytes." (PMID 35103095, 2022). "Persistent hyperglycemia in pancreatic islets induces ROS accumulation, leading to elevated thioredoxin-interacting protein (TXNIP), activation of the NLRP3 inflammasome, and induction of caspase-1-dependent IL-1β maturation." (PMID 35844498, 2022). "Another NLRP3 inflammasome inhibitor, MCC950, has also been shown to prevent hyperglycemia-induced retinal vascular damage, retinal thinning, retinal leakage as well as IL-1β release." (PMID 36430950, 2022). "Hyperglycemia can also induce overexpression of thioredoxin-interacting protein (TXNIP), which plays a critical role in the TXNIP-dependent NLRP3 inflammasome activation." (PMID 34631209, 2021). "Previous studies have demonstrated that hyperglycemia activates the innate immune response mediated by TLR2, TLR4, and the NLRP3 inflammasome, inducing the production of various proinflammatory cytokines, including IL-1β, IL18, IL-6, and TNFα." (PMID 34356130, 2021). "Prolonged hyperglycemia in pancreatic islets induces ROS accumulation, which results in elevation in TXNIP to activate NLRP3 inflammasome activation and to induce caspase-1-dependent IL-1β maturation." (PMID 34631209, 2021). "Overall, THJ protected the heart from hyperglycemia-induced oxidative stress and inflammation in DCM mice via a mechanism involving SIRT1-mediated antioxidant proteins and suppression of the NLRP3 inflammasome." (PMID 33637069, 2021). "Meanwhile, NLRP3 inflammasome activation contributes to the onset of renal disorder in STZ-treated mice and it is triggered by hyperglycemia in GECs." (PMID 32992874, 2020). "To evaluate the role of hyperglycemia in affecting the inflammatory response of KCs in TAA‐induced liver injury, we compared NLRP3 inflammasome activation in KCs isolated from different groups." (PMID 31625631, 2020). "ZDF animals with Type 2 diabetic painful neuropathy revealed a significant increase in NLRP3, HMGB1, and TLR4 in DRG at eight weeks after hyperglycemia when compared to their control counterparts." (PMID 32019145, 2020). "In conclusion, the results of this study demonstrated that hyperglycemia inhibited AMPK/mTOR‐mediated autophagy induction, leading to enhanced NLRP3 inflammasome activation in KCs and increased TAA‐induced acute liver injury." (PMID 31625631, 2020). "Based on the results, Gas inhibited hyperglycemia-induced ERS and NLRP3 inflammasome activation and increased BDNF expression in the hippocampal neurons." (PMID 30524286, 2018). "Previous studies have found that sustained hyperglycemia triggers the production of ROS, which directly or by stimulating the release of thioredoxin interacting protein (TXNIP) indirectly activate NLRP3 inflammasome formation." (PMID 28182085, 2017). "Mechanistically, hyperglycaemia and accumulation of advanced glycation end products (AGEs) can activate inflammatory signalling pathways, including NF-κB, MAPK, and the NLRP3 inflammasome, leading to increased cytokine production, immune dysregulation, and oxidative stress." (PMID 41737225, 2026). "Hyperglycemia, a defining feature of T2DM, also serves as a potent stimulus for NLRP3 activation." (PMID 40648980, 2025). "Oxytocin preconditioning reduced the expressions of NLRP3 and pyroptosis‐related proteins in cardiomyocyte in both normoglycaemia and hyperglycaemia condition under H/R insults." (PMID 39929748, 2025).
Hyperglycemia (continued). "Although hyperglycemia is one of the factors that initiates the triggering of the NLRP3 inflammasome, the exact relationship between hyperglycemia and the inflammatory reaction has not been fully investigated." (PMID 40079000, 2025). "We observed that hyperglycemia did not change the expressionof NLRP3 mRNA at either 30 mM and 50 mM d-glucose-treatedARPE-19 cells compared to normoglycemic control." (PMID 40758602, 2025). "Hyperglycemia induces reactive oxygen species (ROS) overproduction, advanced glycation end products (AGEs) accumulation, and endoplasmic reticulum stress (ERS), which collectively activate key inflammatory pathways (NF-κB, NLRP3, cGAS-STING)." (PMID 41296389, 2025). "Under metabolic stress conditions, such as obesity and hyperglycemia, these macrophages can be activated through receptors such as TLR4 and RAGE, triggering the NF-κB and NLRP3 inflammasome signaling pathways and promoting the release of pro-inflammatory cytokines such as IL-1β and TNF-α." (PMID 41321403, 2025). "Hyperglycemia-induced pyroptosis in human retinal microvascular endothelial cells (HRMECs) is characterized by increased caspase-1 activity, IL-β, NLRP1, NOX4, TXNIP, and NLRP3 expression." (PMID 38645427, 2024). "The NLRP3 inflammasome thereby is primed and/or activated by several metabolites such as FFAs, IAPP aggregates, AGEs and SAA and their downstream effects including ROS induction, release of DAMPs, hyperglycemia, ER stress and GPR signaling." (PMID 37239938, 2023). "NLRP3 silencing or thioredoxin interacting protein (TXNIP) silencing blocked these alterations in hyperglycemia-induced RMEC and diabetic rat retinas, indicating that the TXNIP pathway mediates NLRP3 inflammasome activation and that inflammasome activation leads to inflammation in DR." (PMID 35813208, 2022). "Furthermore, hyperglycemia induce upregulation of E74-like ETS transcription factor 3 (ELF3), leading to NLRP3 inflammasome activation." (PMID 35844498, 2022). "In THP‐1 cells, PKM2 activators TEPP‐46 and glycolysis inhibitor 2‐DG could reverse the protein increase of NLRP3, IL‐18 and IL1‐β induced by hyperglycemia." (PMID 34904398, 2022). "Other studies indicated that MSC-Exo-derived miR-126 could suppress hyperglycemia-induced inflammation by down-regulating HMGB1, which can bind to TLRs and activate the NLRP3 pathway." (PMID 35047512, 2021). "Previous studies have indicated that MSC-Exo-derived miR-126 can suppress hyperglycemia-induced inflammation by down-regulating high mobility group box-1 (HMGB1) protein, which can bind to TLR2, TLR4, and inflammasomes then help activate the NLRP3 pathway." (PMID 35047512, 2021). "This study reveals that hyperglycemia during treatment with ipilimumab, a CTLA-4 blocking agent, increased cardiotoxicity and reduced mortality of MCF-7 and MDA-MB-231 cells in a manner that is sensitive to NLRP3." (PMID 33096896, 2020). "Moreover, we used a hyperglycemia model in U937 monocytes, showing that the activation of TRPM2 was augmented, and TRPM2-mediated Ca2+ influx was critical for NLRP3 inflammasome activation." (PMID 27731349, 2016). "Key molecular players, including toll-like receptors, the NLRP3 inflammasome, and the c-Jun N-terminal kinase (JNK) pathway, act as mediators between metabolic stress and inflammatory responses, emphasizing the bidirectional relationship between inflammation and hyperglycemia." (PMID 41578487, 2026). "Dulaglutide has been shown to reduce hyperglycemia-induced endothelial injury, potentially by preserving sirtuin 1 (SIRT1) levels and curbing mitochondrial fission, as well as via the downregulation of the NLR family pyrin domain containing 3 (NLRP3) inflammasome." (PMID 41008590, 2025). "Moreover, the NLRP3 inflammasome is closely involved in sterile inflammation, which can be triggered by DKD‐related reactive metabolites and metabolic stimuli, including hyperglycemia, AGEs, and ROS." (PMID 39723074, 2024).
Hyperglycemia (continued). "Previous studies revealed that deletion or overexpression of NLRP3 had no change in IL-1β release and severity of pancreatic injury and could not prevent β-cells from pyroptosis during hyperglycemia." (PMID 35265148, 2022). "Moreover, according to the WB analysis, the NLRP3, P2X7, IL-18, and IL-1β protein levels in the retinas of mice in the treatment groups demonstrated similar trends, indicating that 3TC reduced the inflammatory activity induced by hyperglycemia." (PMID 35410316, 2022). "However, the effect of UCP2 on NLRP3 inflammasome-mediated hyperglycemia and I/R damage is not clear." (PMID 33735403, 2021). "Specifically, under sustained hyperglycemia in DM, HG leads to the overproduction of reactive oxygen species (ROS) leading to thioredoxin (TRX)-interacting protein (TXNIP) to dissociate from TRX, enhancing TXNIP expression and activation of the NLRP3 inflammasome." (PMID 33981238, 2021). "In summary, hyperlipidemia and hyperglycemia in DM rats could decrease hippocampal GLUT3 protein level and increase ERS, leading to decreased BDNF expression by disturbing the ER function and positively suppressing the NLRP3 pathway." (PMID 30524286, 2018). "Production of bioactive IL1β by the NLRP3 inflammasome requires a two‐step process involving initial priming from the toll‐like receptors (TLR) by lipopolysaccharide (LPS) and subsequent activation by hyperglycemia, saturated fatty acids such as palmitate, ROS, oxidized LDL, or cholesterol crystals." (PMID 28544264, 2017). "Moreover, hyperglycemia could impede the expression of HIF‐1α, an anti‐inflammatory hypoxia‐inducible factor‐1α, thereby disrupting the NLRP3/IL‐1β signaling pathway and influencing T lymphocyte differentiation, thereby compromising the body's anti‐inflammatory response against Aspergillus." (PMID 40860300, 2025). "Furthermore, MCC950, an NLRP3 inflammasome inhibitor, ameliorated podocyte injury, renal fibrosis, and renal dysfunction in db/db mice, and gasdermin D (GSDMD) knockdown using small interfering RNA (siRNA) in podocytes reversed hyperglycemia-induced inflammation and cell death." (PMID 37373116, 2023). "In addition to hyperglycemia-induced ROS overproduction, oxidized LDLs (oxLDLs) and high mobility group box Protein 1, two well-known agonist ligands of the receptor of AGEs (RAGE), have been involved in the activation of NLRP3 that accompanies the atherosclerotic process." (PMID 32751658, 2020). "Along these lines, advanced glycation end products (AGEs), resulting from non-enzymatic glycation of plasma proteins during hyperglycemia and thus increased in T2DM patients, have been shown to upregulate NLRP3 expression." (PMID 37239938, 2023). "In this study, the protein level of inflammasome components, NLRP3 and ASC, was not affected by Exendin-4-treated hyperglycemia cultured cardiomyocytes, while the upstream activator of inflammasome, TXNIP, was downregulated significantly." (PMID 31886288, 2019).
liver fibrosis (211 papers, 2013 to 2026). "The results showed that NLRP3 knockout reverses the impairment of hepatic bile acid metabolism caused during CCl4-induced liver fibrosis." (PMID 40689656, 2025). "To test the role of NLRP3 in liver fibrosis, we used NLRP3 knockout (NLRP3−/−) mice and intraperitoneally injected CCl4, which has been proved to cause liver fibrosis." (PMID 38172440, 2024). "The NLRP3 inflammasome seems to be of particular relevance in causing liver fibrosis in metabolic liver disease." (PMID 38672492, 2024). "In conclusion, our research showed that liver fibrosis can cause a disorder of BA metabolism, and the dysfunctional bile acid can cause inflammation and activate HSCs through NLRP3 inflammasome, thus further aggravating liver fibrosis." (PMID 38172440, 2024). "In the present study, prolonged inhibition of SIRT1 results in persistent activation of NLRP3 and triggers the production of pro‐inflammatory cytokines, such as IL‐1β, in age‐associated liver fibrosis." (PMID 36999514, 2023). "In conclusion, the present study defines the mechanism by which age‐related SIRT1 loss induces the NLRP3 inflammatory pathway and promotes severe and persistent liver fibrosis during aging." (PMID 36999514, 2023). "When liver fibrosis progresses, chronic inflammation generally causes macrophages to secrete various inflammatory cytokines, which directly activate HSCs and affects NLRP3 inflammasome induction." (PMID 36834849, 2023). "The induction of IL‐1β was further amplified by threefold in SIRT1 LKO mice, suggesting the presence of NLRP3+ cells and elevation of IL‐1β as key pathological features of liver fibrosis associated with SIRT1 loss." (PMID 36999514, 2023). "Age‐dependent inhibition of the longevity factor SIRT1 causes induction of the NLRP3 inflammasome and leads to severe and persistent liver fibrosis in old mice even after the cessation of liver injury." (PMID 36999514, 2023). "We demonstrate, for the first time to our knowledge, that age‐dependent loss of SIRT1 is linked to activation of the NLRP3 inflammasome and perpetuates the progression of liver fibrosis." (PMID 36999514, 2023). "Recently, some studies have reported that the nod-like receptor protein 3 (NLRP3) inflammasome is associated with liver fibrosis." (PMID 36900523, 2023). "As a direct trigger and amplifier of NLRP3 inflammasome activation, ROS is reported to be closely associated with liver fibrosis progression." (PMID 36429008, 2022). "Activation of the NLRP3 inflammasome has been shown to cause liver injury and hepatic fibrosis in various acute and chronic liver diseases." (PMID 35694250, 2022). "In this study, since S100A8-induced NLRP3 inflammasome-dependent pyroptosis is correlated with liver fibrosis, its diagnostic value for the onset and progression of liver fibrosis was analyzed." (PMID 36429008, 2022). "The NOX4/NLRP3 inflammasome pathway plays a crucial role in liver fibrosis and is closely associated with the beneficial effect of UA." (PMID 34530693, 2021). "Considering the pathogenic importance of NLRP3 inflammasome-induced pyroptosis in liver fibrosis, we measured the levels of key markers for pyroptosis, including NLRP3, pro-caspase-1, cleaved Caspase-1, cleaved GSDMD-N, IL-1β, and IL-18." (PMID 34839365, 2021). "Herein, we review current studies about the impact of autophagy and NOD-like receptors containing pyrin domain 3 (NLRP3) inflammasome on liver fibrosis and the underlying mechanisms." (PMID 32733951, 2020). "The main purpose of this review is to systematically summarize the effects of autophagy and NLRP3 inflammasome on liver fibrosis and the underlying mechanisms." (PMID 32733951, 2020). "Several researchers pointed out that NLRP3 inflammsome deficiency has a protective effect against carbon tetrachloride (CCl4) or thioacetamide (TAA)-induced liver fibrosis, and that it reduces mortality and liver injury after acetaminophen administration." (PMID 30635040, 2019).